MAPK12 (mitogen-activated protein kinase 12)
Diseases named in the same sentence as MAPK12 in open-access papers:
MAPK12 is named in the same sentence as 37 diseases in open-access papers, as found by Europe PMC text mining. Sharing a sentence is not in itself a finding about the gene and the disease. The quoted sentences say what the papers report.
breast carcinoma (7 papers, 2012 to 2025). "Similarly, mitogen-activated protein kinase (MAPK12) has been associated with cancer stem-like cell stimulation in breast cancer." (PMID 41302034, 2025). "In addition, MAPK12 is associated with breast cancer, while XRCC2 is part of BCDX2 complex, which acts downstream of BRCA2 recruitment and upstream of RAD51 recruitment." (PMID 31870274, 2019). "A recent study revealed that high MAPK12 expression promoted EMT in breast cancer cells, and the downregulation of MAPK12 inhibited EMT." (PMID 41473739, 2025). "A previous study revealed that MAPK12 significantly increased EMT and promoted CSC regulation in breast cancer." (PMID 34059086, 2021).
colon cancer (3 papers, 2020 to 2024). "Our findings align with previous studies that have demonstrated the influence of MAPK12 overexpression on the prognosis of patients with pancreatic, bladder, and colon cancer." (PMID 38773060, 2024). "Our gene expression analysis also shows differential expression for some of the genes of the MAPK pathway, such as Mitogen-Activated Protein Kinase 3 (MAPK3), Mitogen-Activated Protein Kinase 12 (MAPK12), which were upregulated and downregulated, respectively, in the AA colon cancer cell lines." (PMID 36531053, 2022). "MAPK12, one of four types of p38 MAPK, is a potential therapeutic target for colon cancer." (PMID 32843852, 2020).
amyotrophic lateral sclerosis (2 papers, 2015 to 2021). Amyotrophic lateral sclerosis (ALS) is a neurodegenerative disease characterized by progressive muscular paralysis reflecting degeneration of motor neurons in the primary motor cortex, corticospinal tracts, brainstem and spinal cord. "NF-L binds to Mapk12 (mitogen-activated protein kinase 12), Mapk13, Mapk14, Nefh (neurofilament), Nefm, Prph (peripherin) and Prph2 which are involved in pathway associated to Amyotrophic Lateral Sclerosis (ALS)." (PMID 25561935, 2015).
diffuse large B-cell lymphoma (2 papers, 2024 to 2025). "However, there is still uncertainty regarding MAPK12 involvement in diffuse large B-cell lymphoma (DLBCL)." (PMID 38773060, 2024). "Furthermore, although MAPK12’s role in ESCA is largely unexplored, our findings align with its reported oncogenic functions in other malignancies, such as liver cancer and diffuse large B‐cell lymphoma, where it promotes cell motility and survival." (PMID 41473739, 2025).
pancreatic cancer (2 papers, 2022). "Genes that were upregulated in low-MUC1 PDA samples (MAPK12, RASD1, and AMH) were found to be favorable for OS in pancreatic cancer (Human protein atlas)." (PMID 35237602, 2022).
viral infection (2 papers, 2022 to 2023). "In addition, precise mechanisms underlying the regulation of MAPK12 activation and phosphorylation of STAT2 by MAPK12 during viral infection deserve further investigation." (PMID 36148221, 2022). "Considering the key role of MAPK12 in innate immune response, we further asked whether MAPK12 was involved in the regulation of antiviral genes during early viral infection." (PMID 36148221, 2022). "Since MAPK12 is a serine/threonine kinase, it is possible that MAPK12 might modulate the activation of an unidentified tyrosine kinase that is responsible for the phosphorylation of STAT2 at Y690 during the early stage of viral infection." (PMID 36148221, 2022). "We first screened the four p38 isoforms (p38ɑ/MAPK14, p38β/MAPK11, p38γ/MAPK12, and p38δ/MAPK13) as functional differences between the isoforms in the context of virus infection are particularly understudied." (PMID 37345956, 2023). "To further investigate kinases involved in STAT2 activation at the early stage of viral infection, we constructed CDK9 or MAPK12 knockdown A549 cells using specific shRNAs, respectively." (PMID 36148221, 2022).
Alzheimer disease (1 paper, 2025). A progressive, neurodegenerative disease characterized by loss of function and death of nerve cells in several areas of the brain leading to loss of cognitive function such as memory and language. "↓ of kinase expression (5 μM): GSK3β, CDK5, DYRK1A, CAMK2A, MAPK1, MAPK12, MAPK14.Modulation of the hGMSC transcriptome, ↓ expression of genes involved in Alzheimer's pathogenesis.↓ expression of GSK3b and p‐GSK303B2, which plays a key role in Alzheimer's disease." (PMID 39653426, 2025).
Anxiety (1 paper, 2025). Intense feelings of nervousness, tension, or panic often arise in response to interpersonal stresses. "One possible mechanism is that E2 downregulates Mapk12, thereby reducing MAPK-mediated stress responses and anxiety-like behaviors, particularly in the amygdala." (PMID 40427344, 2025).
bladder cancer (1 paper, 2021). "MAPK12, which may be a risk factor for the prognosis of bladder cancer patients, encodes p38γ, which is mainly expressed in the skeletal muscle." (PMID 34702302, 2021).
cardiac hypertrophy (1 paper, 2022). "Calpain-2 catalytic subunit and lumican related to cardiac fibrosis, and mitogen-activated protein kinase 12 (MAPK12) related to cardiac hypertrophy, showed a significantly negative correlation with CO and TAPSE, and a significantly positive correlation with RV/BW." (PMID 35865003, 2022).
diabetes (1 paper, 2025). "KEGG analysis indicated that genes upregulated in the high-MAPK12 group were enriched in pathways including HIF-1 signaling, diabetes-linked AGE-RAGE signaling, Relaxin signaling, diabetic cardiomyopathy, ECM-receptor interactions, and Toll-like receptor signaling." (PMID 40909863, 2025).
esophageal cancer (1 paper, 2025). A primary or metastatic malignant neoplasm involving the esophagus. "For further validation, we explored the role of MAPK12 in the progression of esophageal cancer through in vitro experiments." (PMID 41473739, 2025). "Therefore, this also suggests that inhibition of MAPK12 may suppress EMT and thus affect the invasion and metastasis of esophageal cancer." (PMID 41473739, 2025). "However, the exact mechanisms by which MAPK12, CHAF1B, and GABRB3 are involved in the progression of esophageal cancer have not yet been reported in the literature and warrant further exploration." (PMID 41473739, 2025).
hepatocellular carcinoma (1 paper, 2024). A malignant tumor that arises from hepatocytes. "MAPK12, for example, is substantially expressed in nasopharyngeal and hepatocellular carcinoma and linked to disease prognosis." (PMID 38773060, 2024).
hyperprolactinemia (1 paper, 2025). Abnormally high level of prolactin in the blood. "In the present experiment, we identified a previously uncharacterized MAPK12-miRNA regulatory pathway that controls GCs apoptosis and steroid hormone secretion under hyperprolactinemia conditions." (PMID 39859292, 2025).
lymphoma (1 paper, 2017). A malignant (clonal) proliferation of B- lymphocytes or T- lymphocytes which involves the lymph nodes, bone marrow and/or extranodal sites. "This identified upregulation of TGFβ signalling as the most affected molecular pathway in Eμ-Myc;shBcor lymphomas (Bonferroni corrected P=0.0058), with enhanced expression of TGFβ pathway members (Cited1, Bambi, Acvr2b, Smad3, Mapk12, Tgfb2)." (PMID 28262675, 2017).
osteosarcoma (1 paper, 2024). A usually aggressive malignant bone-forming mesenchymal neoplasm, predominantly affecting adolescents and young adults. "The overexpression of MAPK12 in osteosarcoma tissues and cells enhances cell growth, proliferation, and migration and promotes the progression of osteosarcoma." (PMID 38773060, 2024).
cancer (16 papers, 2016 to 2025). A tumor composed of atypical neoplastic, often pleomorphic cells that invade other tissues. "The p38-MAPK signaling, including p38β (MAPK11) and p38γ (MAPK12), is associated with the development and progression of several types of cancer." (PMID 34777208, 2021). "Downregulation of Mapk12 further aids cancer cells in evading stress-induced apoptosis, enhancing their survival capacity." (PMID 41415031, 2025). "Specifically, in triple-negative breast cancer, overexpression of MAPK12 facilitates the expansion of tumor stem cell and cell transformation, thereby accelerating cancer progression." (PMID 38773060, 2024). "Our study investigated the expression of MAPK12 mRNA in various types of cancer using bioinformatic analysis." (PMID 38773060, 2024). "p38 mitogen-activated protein kinase (MAPK) signaling including p38α MAPK (MAPK14), p38β (MAPK11), p38γ (MAPK12) and p38δ (MAPK13) is associated with the development and progression of several types of cancer." (PMID 32894113, 2020). "Lately, although studies have reported interactions between MAPK12 and miRNA, including the demonstrated activation of MAPK12 that promotes cancer stemness properties by inhibiting microRNA, there is no reported evidence on whether miRNA is also involved in the apoptosis in GCs regulated by MAPK12." (PMID 39859292, 2025). "We also noted increased (14-fold) expression of the gene Mitogen-Activated Protein Kinase 12 (MAPK12), which has been shown to play a role in cancer development, invasion, and metastasis." (PMID 37691636, 2023). "MAPK12 also modulates the stemness of various CSC types by inducing tumorigenesis and cancer aggressiveness." (PMID 34059086, 2021). "The analysis revealed that MAPK12, RAPGEF3, and KIT exhibited the most betweenness centrality and all were related to the cancer progression." (PMID 28044124, 2016). "RARRES1, NRIP1, GJB2 and others showed a negative correlation with MAPK12 and might be cancer suppressor genes in DLBCL." (PMID 38773060, 2024). "Of the 186 patients without germline P/LP variants and available cancer genomes–exomes, 41/186 patients had a somatic variant in the DNA damage response pathway (ATRX, ATM, PPM1D, POLE) and 21/186 had a variant in the MAPK-ERK pathway (BRAF, NF1, PTPN11, MAPK12)." (PMID 40072012, 2025).
tumor (14 papers, 2015 to 2025). "In contrast, the association of MAPK12—a gene encoding a stress‐responsive kinase—with poor prognosis suggests a potential role in tumor migration, invasion, and perhaps treatment resistance, mechanisms that are distinct from those of canonical biomarkers." (PMID 41473739, 2025). "In previous studies, MAPK12 has been implicated in the development and progression of various tumor types." (PMID 38773060, 2024). "The poor outcome of the subclonal ANK1 mutation may be caused by upregulation of IL4I1, IDO1, IFNG and MAPK12 which showed potential roles in tumor immune evasion through accumulation of immunosuppressive cells such as regulatory T cells and myeloid derived suppressor cells." (PMID 35962343, 2022). "Subclonal ANK1 mutation is related to adverse outcomes of CRC through increasing IL4I1, IDO1, IFNG and MAPK12, which may cause tumor immune escape through the accumulation of immunosuppressive cells such as regulatory T cells and myeloid derived suppressive cells." (PMID 35962343, 2022). "Considering that our gene enrichment analysis suggests an association between MAPK12 and the stem cell pathway in LIHC, we continued to investigate the effect of MAPK12 on tumor stemness through tumor sphere formation assays." (PMID 40909863, 2025). "Results showed a significant association between MAPK12 expression and M stage, TNM stage, and tumor grade." (PMID 40909863, 2025). "The results of in vitro experiments demonstrated that knockdown of MAPK12 reduced the proliferation, metastasis, and tumor stemness-related sphere-forming ability of LIHC cells." (PMID 40909863, 2025). "P38 mitogen‐activated protein kinase (MAPK12) (also known as P38 γ) has been reported to be expressed in multiple tissues and to promote tumorigenesis and tumor progression." (PMID 41473739, 2025). "As a result of targeting MAPK12 in colorectal cancer can reduce tumor proliferation and induce apoptosis." (PMID 38773060, 2024). "The nature of the connection between MAPK12 and human malignancies requires clarification, given the crucial role of MAPK12 in tumor initiation and growth." (PMID 38773060, 2024). "Our results indicate that silencing MAPK12 has a substantial effect on tumor stemness." (PMID 40909863, 2025). "The activation of MAPK12 might be associated with the stress from the microenvironment and IGFBP7 may be related to tumor angiogenesis." (PMID 33808801, 2021). "Additionally, using MAPK12 inhibitors has been shown to inhibit tumor formation." (PMID 38773060, 2024). "We also found that ANK1 (P = 0.0018), IL4I1 (P = 1.2e−12), IDO1 (P = 0), IFNG (P = 0)and MAPK12 (P = 2.2e−12) are positively correlated with PD-L1 expression in CRC cancer which has been reported to be associated with worse prognosis and counteract effect of tumor-infiltrating lymphocytes." (PMID 35962343, 2022). "Mitogen-activated protein kinase 12 (MAPK12), also known as p38γ, is a member of the p38 MAPK family and plays a crucial role in tumor occurrence and invasion." (PMID 38773060, 2024). "Hence, we hypothesize that MAPK12 likely plays a tumor-promoting role in DLBCL." (PMID 38773060, 2024). "The protein expression of FCRL1, GRIK2, MAPK12, and OR51B5 showed differential level between normal colon tissue and tumor tissue." (PMID 38144182, 2023). "To address the first question, we correlated the microarray-based mRNA expression of the 5 CSA targets (EIF2AK3, MAPK12/p38γ, PAK1, RPS6KA3, and WNK3) in a panel of 60 tumor lines of the NCI, USA, with 83 standard anticancer agents." (PMID 35163434, 2022). "The genes listed as involved in androgen-independent pathway, such as MAPK12, and IGFBP7, all exhibited higher expressions in LNCaP xenograft tumor as compared to cultured cells." (PMID 33808801, 2021). "The LPS-inducible mitogen-activated protein kinase 12 (MAPK12), also known as extracellular signal-regulated kinase 6 (ERK6) or p38-γ, was upregulated 11.7-fold in DC-tumor fusions." (PMID 26605345, 2015).
tumor (continued). "Future in vitro and in vivo studies are warranted to determine whether mentioned drugs (such as DRD2 antagonists, MAPK12 inhibitors, RET inhibitors, or drugs targeting PTN) can inhibit tumor growth and improve survival and quality of life in dogs with PPGL." (PMID 37691636, 2023).
infection (3 papers, 2022 to 2025). The state of being infected such as from the introduction of a foreign agent such as serum, vaccine, antigenic substance or organism. "Several MAPK encoding genes, such as MAPK11, MAPK12, and MAPK13, were significantly up-regulated under HN10 infection and MAPK10 was significantly up-regulated under JDm10 infection." (PMID 35893682, 2022).
bacterial infection (1 paper, 2021). "The genes MAPK12 and JUN were related to the bacterial infection and to the toll-like receptor signaling pathway BP." (PMID 34504189, 2021).
cardiovascular disease (1 paper, 2022). "The role of other genes such as NARS, PKDCC, ARHGDIG, STARD10, and MAPK12 expressed in the hypertrophy stage requires more investigation in cardiovascular disease." (PMID 35625658, 2022).
MAPK12 also shares sentences with these, for which no sentence is quoted: liver cancer (2 papers); atherosclerosis (1); chromophobe renal cell carcinoma (1); colorectal cancer (1); COVID-19 (1); diabetic cardiomyopathy (1); inflammatory bowel disease (1); liver fibrosis (1); lung carcinoma (1); neuroblastoma (1); neurodevelopmental disorder (1); osteoarthritis (1); Salmonella Infections (1); scrapie (1); uterine carcinosarcoma (1); uterine corpus endometrial carcinoma (1).